MRTO4 (MRT4 homolog, ribosome maturation factor)
Description:
Component of the ribosome assembly machinery. Nuclear paralog of the ribosomal protein P0, it binds pre-60S subunits at an early stage of assembly in the nucleolus, and is replaced by P0 in cytoplasmic pre-60S subunits and mature 80S ribosomes.
Synonyms: C1orf33; MRT4; dJ657E11.4
Tractability: Small molecule: a structure with a bound ligand is known. PROTAC: ubiquitination databases record sites on it; its protein half-life has been measured.
Gene: Protein-coding gene on chromosome 1 (19,251,796 to 19,260,128, forward strand). Ensembl gene ENSG00000053372.
Subcellular location: Nucleus, nucleolus; Cytoplasm
Subcellular location (Human Protein Atlas): Nuclear membrane; Nucleoplasm; Nucleoli
Gene Ontology:
Molecular function: protein binding; RNA binding
Biological process: nuclear-transcribed mRNA catabolic process; ribosomal large subunit biogenesis; rRNA processing; ribosomal large subunit assembly
Cellular component: cytoplasm; nucleolus; preribosome, large subunit precursor
Genetic constraint (gnomAD): Loss-of-function variants: 12 observed, 34.21 expected, observed/expected ratio (o/e) 0.35, 90% interval 0.22 to 0.57. The upper end of that interval is the gene's LOEUF score, 0.57, which puts it in group 2 of 6, group 1 being the genes least tolerant of losing a copy. Missense variants: 302 observed, 308.12 expected, observed/expected ratio (o/e) 0.98, 90% interval 0.89 to 1.08. Synonymous variants: 113 observed, 113.43 expected, observed/expected ratio (o/e) 1, 90% interval 0.85 to 1.16.
Homologues: Orthologues: chimpanzee MRTO4 (100% identical), macaque MRTO4 (98% identical), guinea pig MRTO4 (95% identical), dog MRTO4 (94% identical), mouse Mrto4 (93% identical), pig MRTO4 (92% identical), rabbit MRTO4 (92% identical), rat Mrto4 (74% identical), tropical clawed frog mrto4 (74% identical), zebrafish mrto4 (71% identical).
Diseases named in the same sentence as MRTO4 in open-access papers:
MRTO4 is named in the same sentence as 10 diseases in open-access papers, as found by Europe PMC text mining. Sharing a sentence is not in itself a finding about the gene and the disease. The quoted sentences say what the papers report.
hepatocellular carcinoma (1 paper, 2024). A malignant tumor that arises from hepatocytes. "mRNA turnover 4 homolog (MRTO4) is highly expressed in hepatocellular carcinoma (HCC) tissues, and we explored its relationship with HCC." (PMID 39504066, 2024).
parasitic infection (1 paper, 2023). "In order to assess the relationship between parasitic infection and testicular spermatogenic function, we determined the gene expression levels of Herc4, Ipo11, and Mrto4 by qRT-PCR." (PMID 36982803, 2023). "On the other hand, parasitic infection decreased sperm quality and downregulated the expression levels of Herc4, Ipo11, and Mrto4, and these genes were strongly related to spermatogenesis." (PMID 36982803, 2023).
Trichinella spiralis infection (1 paper, 2023). "Trichinella spiralis infection downregulated the gene expression levels of Herc4, Mrto4, and Ipo11, genes closely related to the production and functional expression of sperm, which led to the decrease in sperm count." (PMID 36982803, 2023). "Consistent with previous studies, Trichinella spiralis infection decreased the sperm quantity and quality, and the expression levels of genes related to spermatogenesis were also suppressed including Herc4, Ipo11, and Mrto4." (PMID 36982803, 2023).
cancer (2 papers, 2022 to 2024). A tumor composed of atypical neoplastic, often pleomorphic cells that invade other tissues. "We found that MRTO4 expression was positively correlated with TMB (R=0.27, P=2.0e-07), and TMB in malignant tumors is considered to be a novel biomarker used to predict the impact of immunotherapy on patients." (PMID 39504066, 2024). "Taken together, these findings suggested that MRTO4 may contribute to the development of HCC by mediating RNA synthesis and catalytic activity, thereby participating in cancer-related signaling pathways." (PMID 39504066, 2024).
tumor (2 papers, 2019 to 2024). "MRTO4 expression was positively correlated with tumor mutation burden (TMB) and was positively correlated with most immune checkpoint gene expressions in HCC." (PMID 39504066, 2024). "MRTO4 acts as an independent prognostic and immunological biomarker and is correlated with clinical stage, tumor grade, and drug sensitivity in HCC." (PMID 39504066, 2024). "Secondly, we investigated the relationship between MRTO4 expression and immune cell infiltration, IPS (immunophenoscore), TME (tumor microenvironment) score, TMB (tumor mutation burden), immune checkpoint gene expression, and drug sensitivity in HCC." (PMID 39504066, 2024).
MRTO4 also shares sentences with these, for which no sentence is quoted: Alzheimer disease (1 paper); cardiac hypertrophy (1); cardiovascular disease (1); diabetes mellitus (1); fungal infection (1).